BDNF (brain derived neurotrophic factor)
Diseases named in the same sentence as BDNF in open-access papers (continued):
Sharing a sentence is not in itself a finding about the gene and the disease.
liver disease (9 papers, 2017 to 2025). "Overall, these findings suggest that higher plasma BDNF concentrations are associated with less advanced liver fibrosis and milder portal hypertension in patients with PBC." (PMID 40806277, 2025). "Further investigation is needed to explore the potential role of BDNF as an indicator or biomarker of inflammatory pancreas and liver diseases associated with chronic alcohol consumption." (PMID 29108028, 2017). "This coincides with decreased brain-derived neurotrophic factor, a protein vital for brain health, ultimately contributing to cognitive issues and depressive symptoms in liver disease patients." (PMID 41174538, 2025). "Plasma BDNF levels are strongly influenced by platelet levels, hence the absence or presence of liver disease, as well as daily use of anti-platelet therapy, especially clopidogrel, are significant confounding factors for BDNF levels." (PMID 39768827, 2024). "Available data on BDNF in liver diseases remain inconclusive." (PMID 40806277, 2025). "Furthermore, BDNF can also modulate insulin signaling and liver disease in animal models of cirrhosis and alcohol-induced liver disease." (PMID 37377968, 2023). "However, the implicate of CaMKII/CREB/BDNF signaling on liver tissue, especially in liver disorder, is not clear yet." (PMID 34684653, 2021).
lupus (9 papers, 2013 to 2025). "We recently identified that the precursor of brain-derived neurotrophic factor elevated in antibody-secreting B cell subsets drives the development of systemic lupus erythematosus in a p75NTR-dependent manner, highlighting an immune-modulating role of proBDNF-p75NTR signaling in B cells." (PMID 40727935, 2025). "Therefore, we examined the correlation between enhanced NGF and BDNF levels and lupus systemic activity." (PMID 24223945, 2013). "Furthermore, the expression of brain-derived neurotrophic factor precursor (proBDNF) in peripheral antibody-secreting cells (ASCs, defined as CD19+CD27hiCD38hi) is significantly upregulated, and the presence of proBDNF+ ASCs closely correlates with disease activity in lupus patients." (PMID 39917309, 2025). "More recently, it was also demonstrated that circulating levels of NGF and BDNF are increased in SLE patients, with severe lupus flares showing augmented NT-3 levels." (PMID 31616373, 2019).
Nephropathy (9 papers, 2017 to 2025). A nonspecific term referring to disease or damage of the kidneys. "Expression of BDNF in kidney tissue has recently been reported to be associated with nephropathy, and it has been further proposed as a biomarker for glomerular kidney injury." (PMID 37649642, 2023). "BDNF is expressed in the collecting duct of the kidney and may be associated with urine-concentrating ability in an experimental model of chronic CsA-induced nephropathy." (PMID 29540150, 2018). "Our findings reveal that serum BDNF levels are significantly reduced in type 2 diabetic patients with nephropathy compared to both uncomplicated diabetics and healthy controls." (PMID 41142318, 2025). "The authors proposed that miR-365 had a potential binding site for BDNF and that the increase of miR-365 repressed the protein expression of BDNF and p-TrkB, thereby promoting the kidney damage through BDNF/TrkB signaling axis." (PMID 34768854, 2021). "The present study examined the expression of BDNF and tropomyosin-related kinase (Trk) receptors in an experimental model of chronic cyclosporine A (CsA) nephropathy." (PMID 29540150, 2018). "Brain-derived neurotrophic factor (BDNF) levels are lower in diabetic patients compared to healthy individuals, and may be further affected by nephropathy." (PMID 41142318, 2025). "Significantly lower serum concentrations of BDNF in the study group, in addition to higher urine levels, might suggest that the concentration of serum BDNF decreases in cases of kidney damage." (PMID 36293164, 2022). "Therefore, BDNF probably plays a protective role in inflammatory-vascular interactions involved not only in cognitive dysfunction but also in chronic cardiovascular and kidney disorders." (PMID 39355615, 2024). "This study aimed to evaluate serum BDNF levels in diabetic patients with nephropathy without complications and compare them to levels in healthy control subjects." (PMID 41142318, 2025). "The study highlights significant differences in vitamin D, vitamin B12, folate, zinc, calcium, IL-6, IL-12, and BDNF between diabetic patients with and without nephropathy." (PMID 41142318, 2025).
ocular hypertension (9 papers, 2004 to 2025). Abnormally high intraocular pressure. "Intravitreal delivery of brain-derived neurotrophic factor (BDNF) by injection of recombinant protein or by gene therapy can alleviate retinal ganglion cell (RGC) loss after optic nerve injury (ONI) or laser-induced ocular hypertension (OHT)." (PMID 32872441, 2020). "The role of intraocular BDNF in neuroprotection was shown by inducing ocular hypertension in a mouse either homozygous or heterozygous for BDNF." (PMID 39944766, 2025). "Laser-induced ocular hypertension was used to transiently increase IOP in rats, and TrkB + BDNF was able to significantly attenuate axon loss and RGC loss." (PMID 33920974, 2021). "Numerous studies show that after optic nerve injury and ocular hypertension, when increased BDNF mRNA and protein in the retina are detected, concomitant increase, no change or a decrease in TrkB occur, both early and long-term post-injury." (PMID 32872441, 2020). "BDNF has also been shown to be important in RGC survival in OHT, as BDNF supplementation can preserve RGCs in rodent ocular hypertension models." (PMID 31607867, 2019). "Human recombinant BDNF was dissolved in physiological solution (0.9% NaCl); the effects of repeated intravitreal injections and topical eye BDNF applications were independently evaluated in DBA/2J mice with ocular hypertension." (PMID 25536045, 2014). "Thus, repeated topical eye treatment with BDNF was able to restore visual responses in DBA/2J mice with ocular hypertension as evaluated by P-ERG and VEP recordings." (PMID 25536045, 2014). "Topical eye treatment with BDNF can be pursued to elevate the BDNF retinal level leading to rescue of visual retinal responses in DBA/2J mice during an early stage of retinal degeneration characterized by ocular hypertension although a high concentration/amount of this neurotrophin should be used." (PMID 25536045, 2014). "Treatments with BDNF were carried out in 7 month DBA/2J mice with ocular hypertension." (PMID 25536045, 2014). "Thus, topical eye treatment with BDNF represents a promisingly safe and feasible strategy to preserve visual function and diminish RGC vulnerability to ocular hypertension." (PMID 25536045, 2014).
osteoporosis (9 papers, 2015 to 2024). A condition of reduced bone mass, with decreased cortical thickness and a decrease in the number and size of the trabeculae of cancellous bone (but normal chemical composition), resulting in increased fracture incidence. "We also discovered BDNF as a susceptibility gene implicated in osteoporosis that is biologically meaningful." (PMID 27465306, 2016). "Conceivably, depression-associated BDNF reduction may decrease osteoblast differentiation and reduce new bone formation, facilitating osteoporosis." (PMID 35973996, 2022). "Furthermore, since the protective effect of BDNF against osteoporosis in estrogen-deficient rat models remains unknown, the effect of BDNF on bone remodeling was also examined in an ovariectomized-induced osteoporosis rat model." (PMID 38534361, 2024). "Apoptosis, BDNF, and osteoporosis will likely become the focus of future research related to irisin." (PMID 35627690, 2022). "R13 not only represses AEP expression through blunting its upstream transcription factor C/EBPβ but also blocks AEP activation via BDNF/TrkB pathway-activated Akt and it displays promising therapeutic efficacy toward osteoporosis which is similar to anti-RANKL antibody." (PMID 35973996, 2022). "BDNF within the cement may directly affect osteoblast activity within the defect area and eventually increase new bone formation, preferentially in osteoporosis." (PMID 30423942, 2018). "Therefore, BDNF appears as potential drug suitable to be incorporated in CPCs and to stimulate bone formation during fracture healing in osteoporosis." (PMID 30423942, 2018). "BDNF might either have different effects in osteoporotic and non osteoporotic bone or higher concentrations are necessary for enhanced fracture healing in osteoporosis which should be addressed in future studies." (PMID 30423942, 2018). "Considering previous studies where BDNF promoted osteoblast differentiation, BDNF appears to be a promising growth factor for application in osteoporosis treatment since it did not stimulate osteoclasts." (PMID 31242715, 2019). "Moreover, the BDNF-functionalized cement/MBG composite decreased leukocyte numbers within a physiological range in M3 mAChR KO mice suggesting anti-inflammatory effects and consequently biocompatibility during fracture healing in osteoporosis." (PMID 30423942, 2018).
primary open-angle glaucoma (9 papers, 2015 to 2025). "Oddone identified that individuals diagnosed with open-angle glaucoma demonstrate significantly lower serum concentrations of brain-derived neurotrophic factor (BDNF) in comparison to healthy controls." (PMID 39744428, 2025).
Arthritis (8 papers, 2011 to 2024). Inflammation of a joint. "In particular, it is suggested that reduced BDNF production by the cerebral endothelium, deriving from reduced endothelial NO synthesis, could explain the arthritis-associated reduced activation of neuronal TrkB activation." (PMID 33530359, 2021). "Recent evidence also supports the pro-nociceptive role of BDNF in arthritis pain, with higher plasma BDNF levels observed in patients with knee osteoarthritis compared to healthy controls, positively correlating with self-reported pain levels." (PMID 38254671, 2024). "We conclude that experimental arthritis and TNF-α initiate a BDNF-trkB feed-forward pathway in peripheral sensory neurons, and this up-regulation of BDNF-trkB system may participate in pain sensitization." (PMID 21958434, 2011).
dyslexia (8 papers, 2019 to 2025). A learning disorder characterized by an impairment in processing written words. "Thus, atypical changes in BDNF trafficking provoked by ELS may trigger a causal chain leading to dyslexia by the end-point disruption of the functions of the VWFA, impairing children’s ability to learn the print–sound associations fundamental to beginning reading." (PMID 38436668, 2024). "The theoretical narrative of atypical variations in BDNF signaling aligns well with the habituation adaptation resulting in dyslexia." (PMID 38436668, 2024). "In dyslexia, we have only a single study, but results from a sample of children (aged 6–12) produced strong support for BDNF testing as an early marker for dyslexia." (PMID 33551772, 2020). "The adaptation leading to dyslexia induces alterations in BDNF trafficking, promoting long-term adaptive fitness by protecting against excessive glucocorticoid toxicity but risks reading difficulties by disruptive signaling from the CAN to the attention networks and the reading circuit." (PMID 38436668, 2024). "The authors recommended BDNF testing as a biomarker for dyslexia." (PMID 33551772, 2020). "Thus, ELS alterations in BDNF trafficking, by adaptively buffering the HPA axis but selectively disrupting attentional control over the reading circuit, is consistent with the “habituation” stress adaptation strategy and may become a risk factor for dyslexia." (PMID 38436668, 2024). "Thus, the presence of dyslexia itself could be related to such a change in the BDNF level." (PMID 37786524, 2023). "Although several studies with dyslexia samples have observed high cortisol (HPA curtailed plasticity) and low BDNF (signaling reduced plasticity from both systems), the interaction between the HPA and LC/NE systems in dyslexia is unknown." (PMID 33551772, 2020). "Consequently, measurement of the BDNF level in individuals with IS without dyslexia is recommended in future studies." (PMID 37786524, 2023). "The reduced BDNF level could have contributed to the deficits in abilities noticed in children with dyslexia with and without IS." (PMID 37786524, 2023). "The plasma level of BDNF in the children showing dyslexia with and without IS was lower than that in neurotypical children (p < 0.001), which could have influenced their learning performance." (PMID 37786524, 2023). "The results highlighted a potential chain link between neuroplasticity-related as well as stress-related genes, such as BDNF, Sox4, mineralocorticoid receptor (MR), and GILZ, leftward asymmetries in the amygdala and selective cerebellum lobules, and tendencies for personality disorders and dyslexia." (PMID 31632253, 2019).
Dystonia (8 papers, 2018 to 2024). An abnormally increased muscular tone that causes fixed abnormal postures. "In dystonia, this imbalance could rather be associated with hyperactivation of the BDNF/TrkB signaling, subsequently translating into symptoms such as hyperreflexia, rigidity, and tremor." (PMID 39200225, 2024). "It is possible that these individuals are prone to express higher levels of cortical BDNF, inducing disturbed BDNF/TrkB signaling in the striatum and contributing to the development or progression of dystonia." (PMID 39200225, 2024). "More experimental evidence is required to find the specific role of BDNF and the possible disturbances either in the motor cortex or the striatum that induce motor symptoms in dystonia." (PMID 39200225, 2024). "In this review, we focus on the role of BDNF in corticostriatal plasticity in movement disorders, including PD and dystonia." (PMID 39200225, 2024). "Premature long-term potentiation (LTP), which alters the formation of memory, and an increase in the levels of pro-brain-derived neurotrophic factor (BDNF) and BDNF have been found in these murine models of dystonia." (PMID 35955710, 2022). "Some genome-wide association studies (GWASs) and replication studies have revealed correlations between single nucleotide polymorphisms (SNPs) of the ARSG, BDNF, NALCN, OR4X2, KIAA1715, and OR4B1 genes and dystonia." (PMID 35273550, 2021). "A positive correlation between the increase in the BDNF level and features of dystonia was evident in the early HD stage." (PMID 34768699, 2021). "Perhaps BDNF has a protective effect on the development of neurological symptoms in the early stage (patients with higher BDNF levels showed less slowness of movement), and, in the late stage, a higher BDNF correlated with lower dystonia severity." (PMID 34768699, 2021). "In early HD, higher plasma levels of BDNF were found in patients with less severe bradykinesia (p = 0.04, R = −0.49), more severe dystonia of the trunk (p = 0.04, R = 0.51), and lower limb dystonia (p = 0.02, R = 0.62)." (PMID 34768699, 2021). "In this context, the reduced levels of DA reported in some cases of dystonia could lead to altered TrkB cell surface expression and abnormal BDNF/TrkB signaling in D1-expressing SPNs and D2-expressing SPNs." (PMID 39200225, 2024). "It would be worth exploring deeper whether this downregulation of DA in dystonia would lead to altered sensitivity to BDNF in neurons from the direct pathway and/or in neurons from the indirect pathway." (PMID 39200225, 2024). "Delving into the role of BDNF in DYT-TOR1A dystonia, its childhood onset could indicate changes in plasticity at early development, a period characterized by profuse experience-dependent motor learning." (PMID 39200225, 2024). "Furthermore, some variants in brain-derived neurotrophic factor (BDNF) and apolipoprotein E (APOE) have also been reported to lead to an increased incidence of dystonia, possibly via altered neural plasticity." (PMID 32670041, 2020). "Therefore, the role of BDNF in both PD and dystonia requires further exploration." (PMID 35273550, 2021). "The BDNF/TrkB signaling pathway is one of the pathways altered after L-DOPA treatment in rodent models of PD, which further indicates that dystonia implicates dysregulation of signaling pathways for motor control and plasticity." (PMID 39200225, 2024). "Remarkably, we observed an enhancement of pro-BDNF and BDNF protein level in P26 Tor1a+/Δgag mice, which appears critical for the onset of abnormal neurophysiological phenotype in DYT1 dystonia." (PMID 29504938, 2018). "Our study showed a correlation between a low level of plasma BDNF and greater severity of bradykinesia, but not dystonia of the trunk and lower limb in the early disease stage." (PMID 34768699, 2021).
Dystonia (continued). "The activity-dependent factors and the abnormal plasticity mechanisms may not be two different sources of the pathogenesis in dystonia, but rather the joint result of activity-dependent upregulation of plasticity-related molecules such as BDNF." (PMID 39200225, 2024). "Indeed, there is premature long-term potentiation (LTP) with increased levels of pro-brain-derived neurotrophic factor (BDNF) and BDNF and the accumulation of α-amino-3-hydroxy-5-methyl-4-isoxazolepropionic (AMPA) receptors in striatal spiny neurons of DYT1 dystonia model mice." (PMID 33445430, 2021).
hemorrhagic stroke (8 papers, 2014 to 2025). A stroke caused by a bleed on the brain. "Low levels of BDNF are also related to a higher risk of ischemic and hemorrhagic stroke and poor recovery." (PMID 41409760, 2025). "Moreover, clinical studies show a correlation of the Val66Met BDNF polymorphism with poor clinical outcome following hemorrhagic stroke." (PMID 34572573, 2021). "Previous studies also have shown that BDNF supplemented directly or through cell therapy promotes functional recovery in rodent models of ischemic and hemorrhagic stroke." (PMID 37252187, 2023). "For example, one hemorrhagic stroke study showed that infusion of nano-particle bound rEPO led to more than a two-fold increase in BDNF and NGF expression." (PMID 25942688, 2015). "However, in the present study, the ICH volume seems to correlate positively with BDNF concentration in CSF, implying that different pathophysiology is evident between ischemic and hemorrhagic stroke." (PMID 37252187, 2023).
inflammatory bowel disease (8 papers, 2012 to 2026). A spectrum of small and large bowel inflammatory diseases of unknown etiology. "Moreover, colonic BDNF expression levels were increased in mouse models of inflammatory bowel disease, suggesting a role for BDNF in colonic hypersensitivity." (PMID 22715356, 2012).